RN7SL394P (RNA, 7SL, cytoplasmic 394, pseudogene)
Gene: Miscellaneous RNA gene on chromosome 10 (67,825,310 to 67,825,600, reverse strand). Ensembl gene ENSG00000239942.
Homologues: Orthologues: chimpanzee Metazoa_SRP (99% identical), macaque Metazoa_SRP (92% identical). Paralogues in human: RN7SL1 (85% identical), RN7SL2 (85% identical), RN7SL3 (84% identical), RN7SL220P (81% identical), RN7SL7P (81% identical), RN7SL322P (81% identical), RN7SL296P (81% identical), RN7SL478P (81% identical), RN7SL336P (80% identical), RN7SL45P (80% identical), RN7SL507P (80% identical), RN7SL769P (80% identical), and 702 more.